TLR4 (toll like receptor 4)
Diseases named in the same sentence as TLR4 in open-access papers (continued):
Sharing a sentence is not in itself a finding about the gene and the disease.
tumor (continued). "Function prediction and analysis of Actinomyces illustrated that it can induce high expression of TLR2, TLR4, and NF‐κB in young‐onset CRC and reduce infiltration of CD8+T cells in tumor microenvironment, which could provide a direction for the mechanism study of CRC induced by Actinomyces." (PMID 39234654, 2024). "In particular, the expression values of TLR-2, TLR-3, TLR-4, and TLR-9 on CD3-CD56+ cells increased proportionally with the tumor stage, suggesting that these receptors may be functional as diagnostic and prognostic biomarkers in assessing the progression of GC." (PMID 39594809, 2024). "In addition, LPS‐mediated activation of TLR4, the NF‐κB common mediates miR‐18a‐3p and the expression of miR‐4286, increases cancer cell proliferation and motility, and inhibits the expression of BZRAP1, all of which lead to in vitro tumor progression." (PMID 38685971, 2024). "It has been confirmed in various OSCC cell lines (CAL-27/SCC25/SCC9) that HMGB1, upon binding to TLR4, activates the NF-κB pathway, regulates macrophage polarization by upregulating the expression of IL-10 and TGF-β, and enhances the expression of PD-L1, thus promoting tumor immune escape." (PMID 37897664, 2024). "Recent studies have indicated that miR-340 functions as a tumor suppressor and cell cycle regulator and that miR-340 could affect pyroptosis through NLRP3 inflammasome and the TLR4/NF-kB signaling pathway, subsequently leading to decreased inflammatory signaling." (PMID 36834660, 2023). "Tumor necrosis is functionally mediated by infiltrating monocytes/macrophages, and it has been demonstrated that the mobilization of monocytic myeloid-derived suppressor cells (MDSCs) promotes tumor recurrence after liver transplantation via CXCL10/TLR4/MMP14 signaling." (PMID 36698095, 2023). "More recently, we found that Eritoran inhibited tumor growth through immunomodulation and vascular normalization, and that the carboxyl-terminal sequences of mouse S100A8 were necessary for binding to the mouse TLR4/MD-2 complex using a binding assay and CyClus docking simulation." (PMID 36932197, 2023). "Therefore, the hypothesis was that inhibition of TLR4 by ART-activated CLEC12A would prevent inflammation and restrain tumor progression, since we observed anti-cancer effects of ART in our primary mice studies." (PMID 38144525, 2023). "The proliferation of PY8119 cells in vitro was not enhanced by TLR2−/− M2 BMDM and could not be inhibited by PepO-primed TLR2−/− M2 BMDM, while TLR4−/− M2 BMDM promoted tumor cell proliferation and this could be inhibited by PepO reprograming." (PMID 37925462, 2023). "Growing evidence suggests that TLR4 signaling could act as an ideal target to improve the effectiveness of immunotherapy in HCC, reshaping the immune TME, and potentiating the secretion of various chemokines with anti-tumor activity." (PMID 37345131, 2023). "Therefore, in the current study, we investigated the amount of F. nucleatum and its relationship with the expression of inflammatory genes (TLR-2, TLR-4, TNF-α, IL-6, IL-10, IL-12β, and IL-17) and miRNAs (miR-21, and miR-31) in tumor and adjacent normal tissue of Iranian CRC patients." (PMID 38075864, 2023). "Similarly, CTSK can promote CRC progression by promoting M2 polarization of TAM through a TLR4-mTOR-dependent pathway, while M2 macrophages can secrete chemokines such as IL7 and EGFR to activate the NFκB pathway to further promote tumor tissue invasion and metastasis." (PMID 37930479, 2023). "We next explored whether the absence of either TLR2 or TLR4 affected the anti-tumor properties of PepO in vitro and in vivo." (PMID 37925462, 2023). "However, expressions of NF-κB (RelA) and JNK/pJNK reduced in response to ART in both TLR4-expressed and silenced tumor-bearing mice, indicating that TLR4 was not involved in the anti-cancer effects of ART." (PMID 38144525, 2023).
tumor (continued). "EDA from fibronectin could activate a TLR-4 signaling pathway of dendritic cells (DCs) and fusion protein EDA-OVA, EDA-E7 could stimulate specific CTL killing of OVA expression tumor cells and HPV-E7 infected tumor cells, respectively, in a mouse." (PMID 36851198, 2023). "Moreover, other genes such as TLR4, CD4, COL3A1, and ITGB3 are also of great research value, and whether other genes are also involved in the regulation of tumor bone metastases will be investigated in the later studies." (PMID 37007939, 2023). "Moreover, F. nucleatum-positive CRC tumours show resistance to the chemotherapeutic drug oxaliplatin because F. nucleatum promotes the survival and proliferation of CRC cells via Toll-like receptor 4 (TLR-4)-mediated induction of autophagy in those cells." (PMID 35736432, 2022). "Based on extensive studies of inflammatory preclinical models of disease, it is speculated that eNAMPT may accelerate tumor invasion through its function as damp-related molecular pattern protein (DAMP) in response to hypoxia and mechanical stress and activates toll-like receptor 4 (TLR4) binding." (PMID 35906622, 2022). "Another synthetic TLR4 agonist, GLA-SE, upon single systematic administration, rapidly and dose-dependently increased innate and adaptive immunity in each compartment, with no apparent off-target effects, and resulted in a reduction in metastatic progression in all tumor models examined." (PMID 35745800, 2022). "TLR4 has a negative correlation with the majority of TCGA malignancies, but a positive connection with a small number of tumours, including ACC, CHOL, KIRP, LAML, PCPG, THCA, and THYM, indicating a possible relationship with specific epigenetic stemness traits in the cancer types mentioned." (PMID 35801728, 2022). "Interestingly, recent studies demonstrate that baicalein, a bioactive flavonoid, directly binds to toll-like receptor 4 (TLR4), hence reducing VEGF expression, which leads to the inhibition of tumor growth and angiogenesis and reduces the cancer’s metastatic potential." (PMID 35328794, 2022). "This might indicate that TRIF does not contribute to the TLR4-mediated MG-assisted infiltration of tumor cells, but is required for the protective effect of LPS." (PMID 36224342, 2022). "Because Actinomyces co-occurs with various tumor microbiota and causes microbial dysbiosis in CRC, we speculated that Actinomyces activates the downstream TLR4/NF-κB pathway by regulating the occurrence of gram-negative bacteria." (PMID 36119074, 2022). "Moreover, preparations of a weak TLR4 agonist MPLA (or its synthetic analogue GLA) restored the intratumoral activity of cytotoxic T cells and elevated pulmonary NK cell cytotoxicity, which led to tumor eradication and a reduction in cancer metastasis." (PMID 36678520, 2022). "We found that CD276 and VEGFA expression was significantly positively correlated with the expression of OTUD6B in nearly all types of cancer, so were the immune checkpoint inhibitor genes HMGB1 and TLR4, suggesting that OTUD6B may provide some help for tumor immunotherapy through these targets." (PMID 36052059, 2022). "Activating TLR4 may recede the suppressive inflammatory factors expression, including NF-κB, IL-1β, and IL-18 by the ASCL2 regulation, and induce the inflammatory injury to tumor cells, thereby being involved in the prognosis of this disease." (PMID 36008864, 2022). "Blockage of the Bgn-TLR2 or Bgn-TLR4 interaction in E0771 cells by neutralizing antibodies significantly decreased Tnf mRNA expression in E0771 cells stimulated with recombinant biglycan, suggesting that biglycan regulates TNF-ɑ expression in tumor cells through binding to TLR2 and TLR4." (PMID 33966638, 2021). "In this study, we hypothesized that M3G specifically bound to TLR4 in NSCLC cells, to activate its downstream signaling pathways, to upregulate the expression of PD-L1, and to then attenuate the cytotoxicity of CTL, to promote tumor immune escape." (PMID 33628591, 2021).
tumor (continued). "As inhibition of TLR4, CXCR4 and CCR7 impacted anti-tumor immunity and reduced tumorigenesis (tumor numbers, growth and metastasis), our novel OSCC13 grafting model may be suitable to investigate these and other alternative targeting approaches in particular in combination with radiotherapy." (PMID 34290694, 2021). "Moreover, activation of TLR4 by lipopolysaccharide (LPS) can upregulate programmed death-ligand 1 (PD-L1) levels and thereby attenuate the cytotoxicity of the killer T cells (CTL) and promote the tumor immune escape." (PMID 33628591, 2021). "Platelet-tumor cell interactions mediated by platelet toll-like receptor 4 (TLR4) and tumor cell-released high-mobility group box 1 protein (HMGB1) lead also to the α-granule release and P-selectin exposure, subsequently increasing the number of extravasating tumor cells in lung vessels." (PMID 34322381, 2021). "In addition, the LLC tumor-bearing mice in which endogenous macrophages were depleted by clodronate liposomes were intratumorally injected with WT, TLR4−/−, or MyD88−/− BMDMs primed or not with PcrV." (PMID 34900687, 2021). "In addition, a high expression of TLR4 may improve prognosis through TME regulation that activates the immune system and facilitates tumor cells apoptosis." (PMID 34588497, 2021). "Depending on the tumor type and/or the initiating agent, TLR4 ligation in the tumor microenvironment may have the beneficial effect of activating anti-tumor responses or the deleterious action of promoting non-specific inflammatory responses." (PMID 34771569, 2021). "TLR4 activation induced activation of NF-κB and MAPK signaling pathways, resulting in the release of proinflammatory cytokines (TNF-α, iNOS, COX2, PGE2, NO) favoring EGFR permanent activation as well as the release of anti-apoptosis proteins (Bcl-2, Bcl-xl) allowing tumor cell survival." (PMID 33718169, 2021). "However, MMP2 released by tumor cells may directly affect APCs or other cells within the TME that express TLR2 and TLR4." (PMID 34032639, 2021). "Thereby we eventually did not detect tumor cell-specific upregulation of TLR4 protein expression." (PMID 34025672, 2021). "Nonetheless, TLR4 role in the tumor cell compartment is still lacking." (PMID 33446690, 2021). "On the other hand, AKR1B1 (SMD = 0.3; 95% CI 0.01; 0.60; P < 0.01), CTSK (SMD = 1.52; 95% CI 0.98; 2.06; P < 0.01), MMP2 (SMD = 1.02; 95% CI 0.51; 1.53; P < 0.01), TLR4 (SMD = 0.85; 95% CI 0.34; 1.37; P < 0.01) were up-regulate in cancer groups, which might be the tumor proto-oncogene." (PMID 34646828, 2021). "TLR4−/−, TLR7−/− and TLR9−/− untreated tumors presented significantly small volume compared to WT untreated tumors indicating that these TLRs could be involved in normal tumor development." (PMID 34341449, 2021). "The marriage of TLR4 and inflammasome activation and increased local IL-12 concentration may therefore be a combination that can potently transform the TME into one that is anti-tumor and pro-memory formation." (PMID 34855754, 2021). "Interestingly, TLR3 activation resulted in MSCs secreting some factors with mostly tumor supportive immunosuppressive effect (such as IL1RA and IL10), while TLR4 stimulation leaded to MSCs producing inflammatory and proapoptotic factors (such as IL17, GM-CSF, and TRAIL)." (PMID 34736460, 2021). "However, the supernatants of these tumor cells did not activate TLR-2 or TLR-4 reporter cells, suggesting that HGMB1 (which mediates cell activation primarily via these receptors) is not dominant in regulating neutrophil trafficking to these malignant lesions." (PMID 34876407, 2021). "However, our results suggest that knockout of TLR4 does not have significant effect on the percentages of cytotoxic T cells, and M1 and M2 macrophages in the tumor tissues." (PMID 34385421, 2021). "Therefore, targeting TLR4, could not only protect the liver graft from ischemia/reperfusion injury but also reduce MDSC mobilization to decrease tumor recurrence after transplantation." (PMID 33990548, 2021).
tumor (continued). "As TLR1/2, TLR2/6, TLR4 and TLR5 are the most prominently expressed surface TLRs on NK cells, we investigated whether the co-activation of FcγRs with these TLRs would enhance the cytotoxic activity of NK cells, resulting in improved tumor cell killing." (PMID 34681717, 2021). "Targeting TLR4 signaling by TAK-242 has the potential to reduce innate immune cell infiltration and pro-inflammatory mediators in the colon with a long-lasting impact on tumor growth which could be a benefit for the treatment of UC patients." (PMID 34025672, 2021). "In particular, none of the patients with a local, TLR4-negative tumor died from the disease." (PMID 32424768, 2020). "M1 subtype macrophages differentiate through mainly JAK1/2, STAT1/2, 5, TLR4/NF-κB, P38 MAPK pathway activation, excrete inflammatory cytokines and chemokines, participate in a positive immune response; as such, they are able to kill tumor cells in tumor tissue and foreign pathogens." (PMID 32850623, 2020). "Extracellular HMGB1, known as a “danger signal”, also carries neoantigens from tumor cells, including fragments of DNA, to find specific pattern recognition receptors on DCs such as RAGE (receptor for advanced glycation end products) and TLR4 (Toll-like receptor-4, CD284)." (PMID 32872532, 2020). "In our study, TLR family expression, specifically TLR1, TLR3, TLR4, and TLR6, was upregulated in BD3 tumors in comparison with low-grade budding tumors (both in patient and PDX tumors) suggesting the presence of TLR-mediated alterations in the tumor invasive front." (PMID 32719800, 2020). "Exogenous rhCNB was found to be internalized into tumor cells via the Toll‐like receptor 4 (TLR4) complex, but it was not known whether its immuno‐modulatory and antitumor functions involved entry by this same route." (PMID 31218844, 2019). "Although activation of TLR4 by LPS subsides quickly after continuous administration (tachyphylaxis), continuous administration of Hsp70/90 leads to muscle catabolism, simulating tumor-induced muscle without apparent tachyphylaxis." (PMID 31480237, 2019). "Irg1 induction was still observed when TNF-, IFN-γ-, IL-6-, or TLR4-KO mice were inoculated with tumors, however, we could not rule out the possibility that tumor-derived cytokines influence pResMφ." (PMID 29920191, 2018). "TLR4 could be internalized and not detected during the usual cellular processes of storage and recycling, and thus membranous TLR4 would not correlate with either mRNA expression or immunohistochemical staining of cytoplasm within tumor specimens." (PMID 29416610, 2018). "Also, an interesting TLR-4/Wnt modulation highlighted that the absence of TLR-4 determined resistance to the tumor onset." (PMID 30680070, 2018). "We have furthermore demonstrated lower expression of TLR4 in HPV+ OPSCC compared to HPV– OPSCC tumor tissue, as well as a lack of IL-6 and IL-8 expression in HPV+ cell lines after stimulation with both LPS and LPS-UP, inferring functional changes in the TLR4 signaling pathway of HPV+ disease." (PMID 29416610, 2018). "Tumor cells can release HMGB1 into the local microenvironment, where HMGB1 binds with high affinity to several receptors, such as toll like receptor-2 (TLR-2), TLR-4, TLR-9 and advanced glycation end products (RAGE), which can lead to tumor cell survival, expansion and metastasis." (PMID 30526680, 2018). "Moreover, TLR pathway proteins such as TLR4, SARM1, and HMGB1 may play additional roles related to tumor development." (PMID 29472602, 2018). "Therefore, we seek to investigate whether TLR4 and OPN work together to mediate tumor cell invasion and metastasis." (PMID 29228698, 2017). "Interestingly, the suppression of NK cell cytotoxicity was more remarkable following treatment with LPS and recovered by damping the TLR4 function, suggesting that TLR4 expression on MSC play a crucial role in inhibiting NK cell function in tumor microenvironment." (PMID 29029545, 2017).
tumor (continued). "Among which, DAMPs rather than PAMPs play a main role in activating TLR4 in tumor microenvironment." (PMID 29029545, 2017). "Finally, intratumoral LPS treatment directly affects tumors cells as well as immune cells, thereby explaining why LPS treatment on day 0 has antitumoral effects independent of TLR4 expression in tumor cells." (PMID 28641579, 2017). "However, no statistical relationship was found between TLR4 expression and characteristics such as age, gender, smoking status, tumor size, and SUVmax (median 9.4, and patients were then divided into ≤9.4 group and >9.4 group)." (PMID 28484456, 2017). "Furthermore, multiple receptors interacting with different S100 proteins or S100A8/A9 heterodimers are expressed by both tumor cells and TAMs (SCARA/B, CD36), preferentially by TAMs (AGER, MSR1, TLR4) or by tumor cells (ERBB2), pointing to extensive functional interactions between both cell types." (PMID 27215396, 2016). "RAGE and not TLR4 is constitutively expressed by all GemOE tumor cells." (PMID 26989079, 2016). "In particular, the activation of NLRP3 inflammasome via TLR4 signalling led to IL-1β release after caspase-1 activation, whereas, the activation of caspase-11 was important for both IL-1α release and NLRP3-dependent IL-1β release in the lung of tumor-bearing mice." (PMID 27528423, 2016). "Since there were no additive effects by inhibition of both TLR2 and TLR4, it was suggested that one of these TLRs may be sufficient for tumour cells to utilize biglycan." (PMID 27295191, 2016). "Similarly, protumor functions were observed following TLR4 activation in tumor cells and nontumor host cells." (PMID 28116318, 2016). "However, injection of HepG2 cells transfected with Le-TLR4 or Le-NC recombinant lentivirus into nude mice did not inhibit the growth of tumor." (PMID 26514586, 2015). "The absence of TLR4 resulted in significantly reduced tumor suppression by the PAUF DC vaccine." (PMID 26336989, 2015). "To verify whether TLR4 signaling pathway is involved in PSP-mediated immunomodulation in vivo, we found PSP and ADM treatment significantly decreased the mean weights of tumors than saline treatment in B10 (TLR4+/+) tumor-bearing mice." (PMID 26032186, 2015). "Therefore, chronic activation of TLR4 on TAMs in the tumor niche can induce M2 rather than the M1 phenotype." (PMID 25526031, 2014). "No relation between TLR4 expression and time to tumor recurrence was noted." (PMID 24887394, 2014). "The dynamics of the TLR4-induced immune parameters in the tumor microenvironment could be complex, and is not well studied." (PMID 25120541, 2014). "In addition, our villin-TLR4 mice develop duodenal adenomas with Lgr5+ tumor cells, even in the absence of a genotoxic agent, supporting the idea that TLR4 activates proliferation." (PMID 23691015, 2013). "Furthermore, tumor-bearing mice and clinicopathology were used to verify that the LMW-HA/TLR4/CXCR7 pathway may be critical during the development of PTC, indicating LMW-HA as a possible novel immunomodulatory therapy target for PTC treatment." (PMID 24363762, 2013). "Because TLR2 and TLR4 are expressed on the endothelium and implicated in angiogenesis independent of VEGF, biglycan might stimulate tumour angiogenesis through TLR2 and TLR4 activation." (PMID 22374465, 2012). "However, TLR4 and MyD88 expression were not correlated with other parameters such as tumor stages, nodal status, tumor size or tumor site." (PMID 22583829, 2012). "Other groups have reported that low-dose whole-body RT increased expression of TLR4/MD2 and CD14 expression on murine peritoneal macrophages, leading to increased secretion of anti-tumor cytokines including IL-12 and IL-18, thus indicating that RT increases anti-tumor potential of macrophages." (PMID 23251903, 2012).